CD36 (CD36 molecule (CD36 blood group))
Diseases named in the same sentence as CD36 in open-access papers (continued):
Sharing a sentence is not in itself a finding about the gene and the disease.
Autoimmunity (7 papers, 2021 to 2025). The occurrence of an immune reaction against the organism's own cells or tissues. "CD36 blockade exhibited promising prospects for cancer immunotherapy or combination therapy with anti-PD-1 through inhibiting TI-Treg accumulation and suppression without systemic loss of Treg number and function, thus preventing severe autoimmunity after treatment." (PMID 35948909, 2022). "The interaction of CD36-FcγRIIb has the potential to serve as a therapeutic target for the treatment of autoimmune disorders." (PMID 38762740, 2024). "Here, we present compelling evidence supporting the critical role of CD36 in autoimmunity, specifically in the development of germinal center B cells and the production of autoantibodies." (PMID 38762740, 2024). "This study provides evidence for the potential application of the B-cell CD36-FcγRIIb interaction in autoimmunity." (PMID 38762740, 2024). "CD36 promotes cellular FA absorption, an important step in energy metabolism, and CD36 dysregulation has been shown in autoimmunity." (PMID 35050162, 2022). "Future studies should explore HMGB1’s interactions with TLR2/CD36 in B cells, its role in human autoimmune disorders, and whether its cytoskeletal functions intersect with metabolic pathways like oxidative phosphorylation, which was impaired in cKO B cells." (PMID 40985892, 2025). "Our data indicate that CD36 in B cells is a critical regulator of autoimmunity." (PMID 38762740, 2024). "In addition to its established inhibitory function in autoimmunity, our research revealed a potential novel role of FcγRIIB in the interaction with CD36." (PMID 38762740, 2024). "Similarly, the combined use of anti-CD36 antibody to inhibit the Treg-specific up-regulation of CD36 with anti-PD-1 treatment strengthens the anti-tumor response induced by the anti-CD36 antibody alone without causing any autoimmunity." (PMID 35945203, 2022). "Genetic deletion of CD36 inhibited Treg-mediated immunological suppression of tumor-infiltrating lymphocytes and suppressed tumor growth without eliciting severe autoimmunity, providing promising prospects for cancer treatment." (PMID 35948909, 2022). "CD36 knockout of Treg cells does not induce autoimmunity, but enhances antitumor activity.CD36 mediates palmitic acid-induced metastasis of GC through the AKT/GSK-3β/β-catenin pathway." (PMID 35444235, 2022).
colitis (7 papers, 2013 to 2024). Inflammation of the colon. "Deficiency of CD36 scavenger receptor, mainly expressed in macrophages, has been associated with a more aggressive colitis in mice." (PMID 24155895, 2013). "Collectively, our results provide evidence that dietary LCFAs exacerbate colitis by regulating STAT3 palmitoylation through CD36-mediated endocytosis." (PMID 38233383, 2024). "Our previous research has revealed that a natural PPARγ agonist, madecassic acid, can up-regulate the level of CD36 as well as the frequency of Treg cells in dextran sulfate sodium (DSS)-induced colitis mice." (PMID 35392915, 2022). "The protein expression of CD36, a major player in fatty acid uptake, was also significantly reduced in colitis mice." (PMID 33674694, 2021). "Another published paper has reported that, by preventing the degradation of PPARγ, the expression of CD36 can be enhanced, while the Th17/Treg balance can be restored in mice with colitis, implying the involvement of fatty acid oxidation (FAO) in the effects of PPARγ on Treg responses in vivo." (PMID 35392915, 2022). "Our results revealed an upregulation of CD36 levels in colonic tissues of UC patients, and a high-LCFA diet increased CD36 expression in the colonic tissues of mice with colitis." (PMID 38233383, 2024). "In summary, dietary LCFAs, especially PA, can enter cells through CD36 uptake and participate in the palmitoylation cycle of STAT3, leading to the disruption of the intestinal barrier and exacerbation of colitis." (PMID 38233383, 2024). "Our investigation has indicated that dietary LCFAs can enter intestinal epithelial cells via CD36-mediated uptake and endocytosis, thereby participating in the palmitoylation cycle of STAT3 and exacerbating colonic inflammation, which plays a notable role in the development of UC." (PMID 38233383, 2024). "We found that the PPARγ‐target gene CD36 is upregulated during DSS‐induced colitis on ATMs in wild‐type mice and but not in ATMs from Atg7Ad mice." (PMID 36795015, 2023). "In addition, expression of CD36, a lipid scavenging receptor which is commonly found on M2‐type macrophages and induced on ATMs during lipolysis, was increased on the surface of ATMs in wild‐type mice during DSS colitis." (PMID 36795015, 2023). "Taken together, these data indicated that TQHXD could regulate immune homeostasis in TBI‐induced colitis by modulating the M1/M2 ratios of macrophages and restoring the balance of Th17/Tregs and Th1/Tregs, but it could not exert these protective effects in the absence of CD36." (PMID 37157929, 2023).
Hypoglycemia (7 papers, 2007 to 2025). A decreased concentration of glucose in the blood. "Since muscle and adipose tissues shift to high glucose utilization in CD36-deficiency, hypoglycemia and hypoinsulinemia develop in the fasted state in CD36-deficient mice." (PMID 17640331, 2007). "In CD36−/− mice, glucose utilization continued to be enhanced in the heart and red/oxidative skeletal muscle and glucose supply relative to its demand was likely to be diminished, which led to accelerated hypoglycemia." (PMID 30294911, 2018). "Given that glucose seems to be crucial energy substrate for CD36−/− mice even during fasting, our data suggest that accelerated hypoglycemia due to CD36 deficiency and fasting could cause detrimental effects on exercise endurance of skeletal muscle in fasted CD36−/− mice." (PMID 30294911, 2018).
injury (7 papers, 2020 to 2025). Damage inflicted on the body as the direct or indirect result of an external force, with or without disruption of structural continuity. "Anti-CD36 Abs have been suggested to induce transfusion-related acute lung injury (TRALI) upon blood transfusion, particularly in Asian populations." (PMID 36809299, 2023). "Apoptotic cell alone was reported to increase efferocytic activity via the induction of PPARγ and CD36 in bleomycin induced lung injury mouse model." (PMID 32274896, 2020). "In contact sports, the COMT rs4680 polymorphism has been correlated with susceptibility to head trauma and elite athlete status, while CD36 rs1761667 has been associated with the risk of non-contact injuries." (PMID 41010024, 2025). "CD36 receptors in macrophages were found to mediate inflammatory responses via mitochondrial oxidative stress or activation of the AMPK pathway, and it was also revealed that LPS induces pro-inflammatory polarization of macrophages via CD36 in acute lung injury." (PMID 38840180, 2024).
Thrombocytopenia (7 papers, 2007 to 2024). A reduction in the number of circulating thrombocytes. "When, before being loaded onto the delivery system, Portico underwent one additional flushing to those recommended, the receiving patients showed thrombocytopenia, platelet damage, and CD36-monocyte count were mitigated." (PMID 33721196, 2021). "When, before being loaded onto the delivery system, Portico underwent one additional flushing to those recommended (washed Portico), the receiving patients (#wP) showed thrombocytopenia, platelet damage, and CD36-monocyte count were mitigated." (PMID 33721196, 2021). "Thrombocytopenia was known to be associated with increased risk of P. falciparum malaria with the MFI of PAC1 (Odds Ratio [OR] 34.0, Relative Risk [RR] 4.47, 95% Confidence Interval [CI] 4.904 to 235.7; p < 0.0001) and CD36 (OR 4.2, RR 1.82, 95% CI 0.9824 to 17.96; p = 0.04)." (PMID 32268918, 2020).
acute coronary syndrome (6 papers, 2012 to 2024). Signs and symptoms related to acute ischemia of the myocardium secondary to coronary artery disease. "Taken together, these data demonstrate that the scavenger receptor CD36 is involved not only in pro-atherogenic mechanisms but also in the development of acute coronary syndrome symptoms, which are primarily caused by plaque rupture at sites of thrombus formation." (PMID 24965703, 2014). "Previous studies revealed highly upregulated expression of CD36 in circulating monocytes of patients with acute coronary syndromes, infectious diseases like HIV infection and chronic hepatitis B-infected patients with anxiety." (PMID 39524404, 2024). "The FFA transporter, CD36, expressed in macrophages was down-regulated, leading to a reduction of lipids and inflammation in patients suffering from acute coronary syndromes." (PMID 33920678, 2021).
age-related macular degeneration (6 papers, 2012 to 2025). Age-related loss of vision in the central portion of the retina (macula), secondary to retinal degeneration. "CD36 deficiency has been shown to be associated with downregulation of COX-2 in a rodent model of age-related macular degeneration, and CD36 activation has been proposed to increase the expression of COX-2." (PMID 29202856, 2017). "We here analyzed the effect of CD36 deficiency on retinal inflammation and photoreceptor degeneration, the hallmarks of age-related macular degeneration (AMD), that characterize Cx3cr1−/−mice." (PMID 31969887, 2019).
Anxiety (6 papers, 2016 to 2025). Intense feelings of nervousness, tension, or panic often arise in response to interpersonal stresses. "Dietary resveratrol and LA intake may alleviate HFFD‐induced neuroinflammation, systemic inflammation, and anxiety‐like behavior and improve memory, as CD36 may be an underlying mechanism." (PMID 39619979, 2024). "Although there are limited studies, CD36 may be associated with impaired memory and learning ability instead of anxiety." (PMID 39619979, 2024). "In males born by vaginal delivery, the expression of Cd36 at PND64 was correlated to anxiety at PND55, whilst a correlation between the expression of Clec7a and the number of head dippings in the elevated plus maze was also noted in males born by CSD." (PMID 39616177, 2024). "Recent studies showed that CD36-/- mice have behavioral phenotypes that include increased anxiety, aggression and locomotor activity." (PMID 27503363, 2016). "Further, the present study revealed that low plasma CD36 may indicate increased recognition memory and reduced anxiety‐like behavior." (PMID 39619979, 2024). "Importantly, new studies show that CD36-knockout mice have behavioral traits that include increased aggression, anxiety and locomotor activity." (PMID 27503363, 2016). "CD36 is widely expressed, but areas of the amygdala and hypothalamus are among the brain regions with highest enrichment; and CD36-knockout mice are known to have significantly increased anxiety and aggression." (PMID 27503363, 2016).
brain injury (6 papers, 2020 to 2025). Acute and chronic (see also brain INJURIES, CHRONIC) injuries to the brain, including the cerebral hemispheres, CEREBELLUM, and brain STEM. "The unexpected increase in both myelin and lipid accumulation observed in Cd36 and Trem2 deficient microglia and monocytes following brain trauma may reflect redundancy and compensatory mechanisms among scavenger receptors." (PMID 40964307, 2025). "While earlier research emphasized CD36’s involvement in lipid metabolism, recent studies have identified its role in the neuroinflammatory processes underlying several central nervous system (CNS) diseases such as ischemic brain injury, Alzheimer’s disease, and spinal cord injury." (PMID 38840180, 2024). "Nevertheless, the precise role and function of CD36+ MGs/MΦs after brain injuries require elucidation in future studies, including human samples." (PMID 39451255, 2024). "Furthermore, there is increasing evidence that CD36+ MGs/MΦs promote the phagocytosis of myelin debris after various brain injuries, thereby reducing neuroinflammation and promoting remyelination." (PMID 39451255, 2024).
carotid atherosclerosis (6 papers, 2016 to 2025). A thickening and loss of elasticity of the walls of carotid arteries that occur with formation of atherosclerotic plaques. "The possibility that other markers related to the CD36 protein such as CD36-associated MP as well as its main cellular source could be a biomarker of subclinical carotid atherosclerosis should be further explored." (PMID 32498389, 2020). "CD36 expression at the protein level has been shown to be significantly increased in patients with carotid atherosclerosis, particularly in the advanced stages of the disease." (PMID 40002707, 2025). "The photoacoustic signal reflects CD36(+) expression in plaques, which shows the feasibility of using photoacoustic imaging for in vivo assessment of carotid atherosclerosis." (PMID 32292523, 2020).
Cognitive impairment (6 papers, 2020 to 2024). Abnormal cognition is characterized by deficits in thinking, reasoning, or remembering. "CD36 promotes vascular amyloid deposition and leads to vascular brain damage, neurovascular dysfunction, and cognitive deficits." (PMID 35619150, 2022). "We investigated the role of CD36 in BAM in the neurovascular and cognitive dysfunction, and in the underlying parenchymal and vascular amyloid deposition in 15-month-old Tg2576 mice with florid amyloid pathology and cognitive impairment." (PMID 37162996, 2023). "First, we established a BM transplantation-based strategy to selectively delete CD36 from BAM in 15-month-old Tg2576 mice with extensive CAA and cognitive impairment." (PMID 37162996, 2023). "Nrf2 up-regulation ameliorated cognitive impairment in APP Knock-in AD mice, and in APPswe/PSEN1dE9 hypoxic mice, the intranasal administration of Nrf2 modulated CD36 protein expression, reduced Aβ deposition, and improved spatial memory." (PMID 33276671, 2020). "Although HFFD did not lead to cognitive impairment in the present study, DI values were positively correlated with brain IL‐10 and negatively correlated with plasma CD36 and IL‐6." (PMID 39619979, 2024).
head and neck cancer (6 papers, 2019 to 2025). A primary or metastatic malignant neoplasm affecting the head and neck. "To further explore the molecular context of CD36, we analyzed RNA-seq data from 288 patients with head and neck cancer in TCGA Head and Neck Squamous Cell Carcinoma (HNSC) cohort." (PMID 41465497, 2025). "Our finding of CD36 high expression in samples with lymph node metastasis is commensurate with a recent report showing that CD36 overexpression characterized head and neck cancer stem cells that drive metastasis." (PMID 31655604, 2019). "Taken together, these findings suggest that CD36 could be a promising therapeutic target for clinical intervention of head and neck cancer." (PMID 37927468, 2023). "In this study, we have investigated whether oxLDL, largely involved in atherosclerosis progression, impacts the expression of two oxLDL receptors, CD36 and Lox-1, in head and neck cancer (HNC) cell lines." (PMID 34063116, 2021). "In addition, overexpression of crucial components in lipid metabolism, such as cluster of differentiation 36 (CD36), fatty acid-binding protein (FABP), acetyl-CoA carboxylase (ACC), and fatty acid synthase (FASN), have been well-documented in head and neck cancer." (PMID 37927468, 2023).
myocardial ischemia (6 papers, 2020 to 2026). A disorder of cardiac function caused by insufficient blood flow to the muscle tissue of the heart. "The severity of tissue damage has been shown to be mediated by CD36 in brain ischemia and myocardial ischemia‐reperfusion, as well as in acute lung injury induced by H2O2 and lipopolysaccharide." (PMID 39552437, 2024). "Thus, we conclude that modulation of CD36 by azapeptide MPE-298 exhibits therapeutic potential for treating acute myocardial ischemia and reperfusion by supporting metabolic recovery and limiting excess LCFA uptake." (PMID 42098955, 2026). "Moreover, a decrease in oxidative stress was observed in the left ventricle of mice that were treated with a selective azapeptide CD36 modulator before transient myocardial ischemia." (PMID 39552437, 2024). "Another scavenger receptor, Cd36, which is remarkably abundant in cardiac ECs, could alleviate cardiac ischemia-reperfusion injury and has been considered to be a promising therapeutic target for a series of cardiovascular diseases." (PMID 36834610, 2023). "Synthetic analogues of growth hormone releasing peptide-6 (GHRP-6, H-His-D-Trp-Ala-Trp-D-Phe-Lys-NH2, 1, CD36 IC50 1.82 μM) have shown promising cardioprotective effects by binding and regulating CD36 in a mouse model of myocardial ischemia and reperfusion." (PMID 32717955, 2020).
rheumatoid arthritis (6 papers, 2014 to 2025). A chronic, systemic autoimmune disorder characterized by inflammation in the synovial membranes and articular surfaces. "By testing the activation status of NRF2 genes and CD36 by RS, we were able to develop a predictive test of the clinical response to TNFi in patients with rheumatoid arthritis." (PMID 40428231, 2025). "In rheumatoid arthritis (RA), CD36 expression in fibroblasts is increased by macrophage-derived inflammatory mediators, including interleukin-1β (IL-1β), IL-6 and interferon gamma (IFN-γ)." (PMID 37576819, 2023). "In addition to cells of the immune system, CD36 and IL-33 are also found in human OA cartilage and rheumatoid arthritis (RA) synovium, respectively." (PMID 33374841, 2020).
triple-negative breast carcinoma (6 papers, 2014 to 2026). An invasive breast carcinoma which is negative for expression of estrogen receptor (ER), progesterone receptor (PR), and human epidermal growth factor receptor 2 (HER2). "Earlier, we showed that the coculture of the triple-negative breast cancer (TNBC) MDA-MB-231 or Luminal A MCF7 with CD36+ fibroblasts (FBs) induced growth suppression in TNBC MDA-MB-231 and reversion of basal and lateral polarity in the Luminal A MCF7." (PMID 36361532, 2022). "In fact, this basal B-specific splicing signature has highlighted a subpopulation of basal-like triple negative breast cancer patients differentially expressing several hallmarks of invasive, EMT-like aggressive cancer, such as the newly identified biomarker of metastasis CD36." (PMID 33845831, 2021). "It has been recently reported that certain cancer cells such as aggressive triple-negative breast cancer cell lines express markers of lipolysis (lipoprotein lipase, LPL) and exogenous fatty acid uptake (CD36), concomitantly with markers of de novo lipogenesis (FASN)." (PMID 25215509, 2014). "Analysis of gene expression using bc-GenExMiner showed that the mRNA levels of FABP, ADIPOQ, PPARG, CD36, PPARGC1A, and CREBBP were significantly lower in basal-like and triple-negative breast cancer (TNBC) cells than in non-basal-like and non-TNBC cells." (PMID 36114448, 2022).
intracerebral hemorrhage (5 papers, 2017 to 2024). A cerebrovascular disorder characterized by bleeding into one or both cerebral hemispheres including the basal ganglia and the cerebral cortex. "In this study, we aimed to investigate the association between CD36 gene polymorphisms and intracerebral hemorrhage (ICH) in a Han Chinese population." (PMID 28804718, 2017). "In addition, stimulation of CD36 signaling can promote microglial phagocytic capacity and is an important mechanism underlying blood clearance after intracerebral hemorrhage." (PMID 35751629, 2022). "In accordance with the findings in this study, microglial CD36 determines phagocytosis after intracerebral hemorrhage and other cerebral injury modalities." (PMID 38338958, 2024). "Pro‐inflammatory cytokines such as TNF‐α downregulate microglial CD36 expression, leading to impairments in microglial engulfment of the hematoma following intracerebral hemorrhage." (PMID 35751629, 2022).